HLA-DRB5 (major histocompatibility complex, class II, DR beta 5)
Diseases named in the same sentence as HLA-DRB5 in open-access papers (continued):
Sharing a sentence is not in itself a finding about the gene and the disease.
schizophrenia (4 papers, 2019 to 2026). A major psychotic disorder characterized by abnormalities in the perception or expression of reality. "Seven switch genes, NPAS3, ARHGAP15, LGALS3BP, DPP10, SMYD3, CPXCR1, and HLA-DRB5 were associated with known risk factors for schizophrenia." (PMID 36982982, 2023). "The chromosome conformation capture (3C) analysis in human brain cells revealed the architecture of multipoint chromatin interactions between the schizophrenia-associated genetic and epigenetic polymorphic sites and distantly located HLA-DRB5 and BTNL2 genes." (PMID 31624234, 2019). "Likewise, NPAS3, ARHGAP15, LGALS3BP, DPP10, SMYD3, CPXCR1, and HLA-DRB5 were associated with known risk factors for schizophrenia." (PMID 36982982, 2023). "Furthermore, nine loci in this region (HLA-DRB5 and HLA-A) are associated with schizophrenia or autism spectrum disorder." (PMID 34635054, 2021).
systemic sclerosis (4 papers, 2013 to 2023). A chronic disorder, possibly autoimmune, marked by excessive production of collagen which results in hardening and thickening of body tissues. "HLA-DRB5 is highly expressed in the PBMCs of patients with systemic sclerosis (SSc)-related interstitial lung diseases, and the HLA-DRB5*01:05 allele was possibly a risk factor for ILD in patients with SSc." (PMID 38203236, 2023).
asthma (3 papers, 2018 to 2020). "Furthermore, the well-reported asthma-associated genes of HLA-DQA1, HLA-DRB1, and HLA-DRB5 have the most number of interacted edges with identified and predicted genes." (PMID 33066754, 2020). "The genes of HLA-DRB5, HLA-DQA1, HLA-DPB1, CTSW, PSMB9, and TAP2 have the most number of edges with both predicted genes and childhood-onset asthma-related genes." (PMID 32867763, 2020). "Some of the top-ranked significant genes, e.g., HLA-DRB3, HLA-DRB5, and HLA-DRB4, have been widely documented to be involved in mild asthma pathogenesis in previous studies, which is in line with previous finding that there exist shared genetic components between mild and moderate-to-severe asthma." (PMID 33066754, 2020).
colon cancer (3 papers, 2018 to 2025). "Our results show that higher HLA-DRB5 expression in TCM cells 5 d post-activation has a protective effect risk of colon cancer, which aligns with this explanation." (PMID 40974097, 2025). "Our results show that higher HLA-DRB5 expression in TCM cells 5 days post-activation has a protective effect risk of colon cancer, which aligns with this explanation." (PMID 40321251, 2025). "Another major histocompatibility complex family member, major histocompatibility complex, class II, DR beta 5 (HLA-DRB5) is found significantly upregulated in human colorectal cancer epithelial cell and has prognostic value in the prediction of colon cancer metastasis." (PMID 30186855, 2018).
colorectal cancer (3 papers, 2018 to 2025). A primary or metastatic malignant neoplasm that affects the colon or rectum. "In colorectal cancer, HLA-DRB5 expression levels are significantly correlated with the infiltration of CD8+ T cells, CD4+ T cells, and dendritic cells, implying that tumors in the NSTAS group of our samples might exhibit greater immune cell infiltration." (PMID 40786043, 2025).
dementia (3 papers, 2021 to 2025). Loss of intellectual abilities interfering with an individual's social and occupational functions. "The co-twin control results for dementia is thus likely driven by a single spurious finding, and taken together the results indicate the presence of familial confounding also in the association between HLA-DRB5 and dementia or AD." (PMID 36573011, 2023). "Differential leukocyte DNA methylation in association to dementia (at P < 0.05) was detected in HLA-DRB5 and SLC24A4 in the total sample." (PMID 36573011, 2023). "HLA-DRB5 remained significant in co-twin control analyses, while the association between DNA methylation in SLC24A4 and dementia was weakened, indicating that familial confounding partly drive the association." (PMID 36573011, 2023). "Using cohort data of 544 Swedish twins (204 dementia diagnoses), we replicated the findings in HLA-DRB5 and SLC24A4 at P < 0.05." (PMID 36573011, 2023). "The association with HLA-DRB5 remained in twin pairs discordant for dementia, but not AD." (PMID 36573011, 2023). "In conclusion, HLA-DRB5 and SLC24A4 are not only differentially methylated in cortical cells from AD patients compared to controls, but also in leukocytes collected pre-mortem in relation to dementia." (PMID 36573011, 2023).
diabetes (3 papers, 2011 to 2025). "In the combined analysis of genes unique to DR and those in common with diabetes mellitus at the threshold of <0.05, we identified C2, C4A, CD8A, HLA-DRB5, and HLA-DQA2, which have been associated with lymphocyte-mediated immunity (FDR 2.96 × 10−2)." (PMID 38791494, 2024). "Although meta-analyses have shown a positive relationship between HLA-DRB5 deficiency and diabetes risk, there is a lack of reports linking HLA-DRB5 to DKD pathogenesis." (PMID 40427057, 2025).
sarcoidosis (3 papers, 2012 to 2023). Sarcoidosis is a multisystemic disorder of unknown cause characterized by the formation of immune granulomas in involved organs. "This same study identified HLA-DRB9 and HLA-DRB5 as associated with sarcoidosis risk." (PMID 38390497, 2023). "We replicated associations for several previously reported sarcoidosis susceptibility risk loci in our AA collection including MHC Class II region genes (HLA-DRA, HLA-DRB5, HLA-DRB1, and HLA-DQA1), BTNL2, RAB23, and ANXA11." (PMID 22952805, 2012).
aortic root dilatation (2 papers, 2012 to 2021). "Marfan syndrome patients with progressive aortic root dilatation have increased expression of HLA-DRB5, which indicates an increase in the inflammatory response corresponding to progressive aortic disease." (PMID 34852854, 2021).
autism spectrum disorder (2 papers, 2021 to 2023). A spectrum of developmental disorders that includes autism, and Asperger syndrome. "HLA-DRB5 encodes a protein involved in the immune response by presenting peptides derived from extracellular proteins, and its DNA methylation pattern has also been associated with neurological diseases, including autism spectrum disorder and Alzheimer." (PMID 36400229, 2023).
coronary artery disease (2 papers, 2017 to 2024). "Notably, genes like HLA-DRB1 and HLA-DRB5, situated in or near the human major histocompatibility complex (MHC) on chromosome 6, exhibit associations with immune diseases (e.g., autoimmune thyroid disease) and cardiovascular traits (e.g., coronary artery disease)." (PMID 38384714, 2024). "One SNP, rs76846904, close to the HLA-DRB5 gene, is highly correlated with CFB gene expression in subcutaneous adipose tissue (effect size, 0.78; P=0.000015) and within 100 kb of GWAS hits for visceral adiposity, serum cholesterol, and coronary heart disease." (PMID 28739975, 2017).
depression (2 papers, 2023 to 2025). "The increased expression of HLA-DRB5 identified in patients with depression vs controls appears mainly driven by patients with persistent depression." (PMID 40585350, 2025). "Two genes, MTC01P12 (Log2FC = 4.67, pAdj = 0.007) and HLA-DRB5 (Log2FC = 9.14, pAdj = 0.001) were found to be significantly upregulated in the depression group when compared with controls." (PMID 40585350, 2025).
dyslipidemia (2 papers, 2017 to 2022). "Downregulation of HLA-DRB4 in peripheral blood mononuclear cells is associated with T2D as well as dyslipidemia and periodontitis, while a meta-analysis revealed that the lack of HLA-DRB5 increased T2D risk." (PMID 35788821, 2022).
mucositis (2 papers, 2017 to 2022). Mucositis is inflammation and damage of the mucous membranes lining the mouth and other parts of the gastrointestinal (GI) tract. "HLA-DRB5 was expressed at low levels in all patients with multiple myeloma, in a subgroup of patients with ulcerative mucositis and in a control group." (PMID 36147484, 2022). "Furthermore, our results suggested that the expression levels of HLA-DRB1 and HLA-DRB5 may serve as potential predictive biomarkers for mucositis severity." (PMID 28052121, 2017).
multiple myeloma (2 papers, 2022 to 2023). "We find that high expression of the MHC-II molecule HLA-DRB5 on myeloma cells strongly associated with ex vivo elotuzumab response." (PMID 37081258, 2023). "In line with that interpretation, we observe that patient samples with high myeloma expression of HLA-DRB5 present with increased cell–cell contacts between myeloma cells and activated T cells upon ex vivo elotuzumab treatment." (PMID 37081258, 2023). "Across the cohort, we observed increased interactions between myeloma cells and activated T cells upon elotuzumab treatment for HLA-DRB5-high MM samples compared to HLA-DRB5-low samples, suggesting that MHC-II-mediated antigen presentation associates with increased sensitivity to elotuzumab." (PMID 37081258, 2023).
periodontitis (2 papers, 2021 to 2022). An acute or chronic inflammatory process that affects the tissues that surround and support the teeth. "In endothelial cells, HLA class II molecules HLA-DRB5 and CLEC3B associated with extracellular proteolysis were upregulated in periodontitis." (PMID 34566966, 2021).
prostate carcinoma (2 papers, 2022 to 2025). A carcinoma that arises from epithelial cells of the prostate gland. "HLA-DRB5 was highly related to MHC-II genes, which were the related genes of prostate cancer, and so was the CHRNB2." (PMID 36376815, 2022).
tuberculosis (2 papers, 2022). A chronic, recurrent infection caused by the bacterium Mycobacterium tuberculosis. "A first genome-wide association study (GWAS) on tuberculosis in Han Chinese revealed HLA loci, rs41553512 (a missense mutation in HLA-DRB5), significantly associated with tuberculosis." (PMID 35664353, 2022). "Our finding was in agreement with a 2017 study of susceptibility loci associated with tuberculosis in Han Chinese which reported that candidate genes that were significantly associated with TB included among others genes in the HLA-DRB5." (PMID 35519172, 2022).
anaphylaxis (1 paper, 2025). An acute hypersensitivity reaction that occurs from exposure to an allergen. "We identified an association between the rs192498095 variant in HLA‐DRB5 and cefaclor‐induced anaphylaxis based on WES data." (PMID 40974473, 2025). "Genetic variants in TPSAB1 and HLA‐DRB5 may contribute to the risk of cefaclor‐induced anaphylaxis, and TPSAB1 may also be associated with severity." (PMID 40974473, 2025). "Furthermore, the co‐occurrence of rs765144578 variant in TPSAB1 and rs192498095 variant in HLA‐DRB5 demonstrated a markedly stronger association with anaphylaxis than either variant alone." (PMID 40974473, 2025). "Taken together, TPSAB1 and HLA‐DRB5 emerge as meaningful genetic contributors to cefaclor‐induced anaphylaxis based on both biological plausibility and case–control association signals." (PMID 40974473, 2025). "In contrast, the HLA‐DRB5 and the TPSAB1 are more plausibly implicated in drug induced anaphylaxis." (PMID 40974473, 2025).
bare lymphocyte syndrome (1 paper, 2017). "To that end, we used liquid chromatography couple to tandem mass spectrometry (LC–MS/MS) to characterize the peptide repertoires associated with HLA-DRB1*15:01 (555 unique peptides) and HLA-DRB5*01:01 (169 unique peptides) from bare lymphocyte syndrome (BLS) transfected cells." (PMID 28871256, 2017).
Cachexia (1 paper, 2022). Severe weight loss, wasting of muscle, loss of appetite, and general debility related to a chronic disease. "B cells from patients with cachexia showed lower expression of MHC-II molecules (HLA-DRB5, HLA-DQA2) and higher expression of the immunoglobulins (IGHG2, IGHG3, IGKC), and genes involved in BCR signaling." (PMID 36376273, 2022).
cervical cancer (1 paper, 2022). A primary or metastatic malignant neoplasm involving the cervix. "Studies have shown that HLA-DRB5 is associated with risk factors for cervical cancer." (PMID 36147484, 2022).
coccidioidomycosis (1 paper, 2024). A fungal infection caused by Coccidioides immitis. "For HLA-DRB5, several drugs have been identified, including 1D09C3 for various forms of cancer, Coccidioides immitis spherule for detecting delayed-type hypersensitivity in individuals with a history of pulmonary coccidioidomycosis, and Apolizumab for solid tumors/cancer." (PMID 39092217, 2024).
diabetic retinopathy (1 paper, 2024). "HLA-DRB5 expression levels are related to T2DM status, HbA1c levels and diabetic retinopathy status, and the downregulation of HLA-DRB5 expression is associated with an increased risk of developing T2DM." (PMID 39916961, 2024).
endometrial cancer (1 paper, 2020). Primary or metastatic malignant neoplasm involving the endometrium (mucous membrane that lines the endometrial cavity). "Our results identified CD74, HLA-DRB5, CD52, HLA-DPB1 and HLA-DRB1 as possible valuable genetic markers for the diagnosis and prognosis of endometrial cancer and provided a theoretical basis for immunotherapy targets for its clinical treatment." (PMID 33159014, 2020).
gastric cancer (1 paper, 2021). A primary or metastatic malignant neoplasm involving the stomach. "HLA-DRB5 has also been considered a possible prognostic factor for gastric cancer." (PMID 34539740, 2021).
gestational diabetes (1 paper, 2023). Carbohydrate intolerance first diagnosed during pregnancy. "In a review study, methylation and gene expression changes were investigated in subcutaneous adipose tissue of pregnant women with gestational diabetes, in which they found that the HLA-DRB5 gene was hypermethylated." (PMID 38140282, 2023).
hepatitis B (1 paper, 2023). "Similar to this result, it was reported that HLA-DRB5 is significantly downregulated in the liver tissue of patients with hepatitis B who showed a poor response to antiviral therapy." (PMID 37593735, 2023).
liver disorder (1 paper, 2024). A disease involving the liver. "The identification of specific drugs targeting HLA-DRB5, GJB3, HSD17B13, and CD244 for various indications, such as cancer, metabolic diseases, and liver disorders, further strengthens their potential as therapeutic targets in LUAD." (PMID 39092217, 2024).
Lyme disease (1 paper, 2016). Lyme disease (named after the towns in the USA where the disease was first identified) is a bacterial infection caused by Borrelia burgdorferi. "Here we found that upregulation of certain HLA genes (HLA-DQA1, HLA-DQB1, HLA-DRB5) is associated with seronegativity in Lyme disease and may thus constitute potential diagnostic biomarkers for seronegative patients." (PMID 26873097, 2016). "While no DEGs were identified on the basis of single versus multiple lesions, four DEGs were found to be upregulated in seronegative Lyme disease patients relative to those who were seropositive, namely, HLA-DQA1, HLA-DQB1, HLA-DRB5, and NSA2." (PMID 26873097, 2016).
MODY (1 paper, 2022). "Specifically, SLC2A2 (GLUT2), and IAPP genes were commonly enriched in MODY, while HLA-DRB4 and HLA-DRB5 genes were underlying the enrichment with T1D." (PMID 35788821, 2022).
Obesity (1 paper, 2024). Accumulation of substantial excess body fat. "Differential gene expression revealed that genes associated with innate immune responses (LYZ), antigen processing and presentation (HLA-DRB1, HLA-DRB5, IFI30), as well as cell signaling and migration (VIM, RGS1, NCF) were upregulated in the HBC subset with pregravid obesity." (PMID 39872537, 2024).
orofacial clefting (1 paper, 2023). "Although HLA‐DRB5 has not been associated with orofacial clefting or limb malformations, it is one of the HLA‐DRB cluster of genes in the HLA region of chromosome 6 and a paralog of the known oral cleft gene HLA‐DRB1, some transcripts of which may overlap." (PMID 37070724, 2023).
pancreatic cancers (1 paper, 2023). "To generate HLA-matched MHC-II+ cell lines for these studies, we transduced the KRASG12V+ cell lines NCI-H2444 and DAN-G, derived from human lung and pancreatic cancers, respectively, with CIITA and a construct encoding HLA-DRB5*01:01 with a truncated CD34 reporter gene." (PMID 36512410, 2023).
pancreatic ductal adenocarcinoma (1 paper, 2023). An infiltrating adenocarcinoma that arises from the epithelial cells of the pancreas. "Identification of an HLA-DRB5*01:01–restricted, KRASG12V-specific TCR from blood of a patient with pancreatic ductal adenocarcinoma." (PMID 36512410, 2023).
parasite infection (1 paper, 2021). "Thus, POR is indirectly responsible for regulation of expression of CIITA along with the molecules of MHC II group such as CD74, HLADQA1, HLADMA, HLADQB1 and HLADRB5 previously identified as genes responsible for inhibition of parasite infection." (PMID 34946170, 2021).
rheumatic diseases (1 paper, 2022). "Some of those significant DEGs above such as HLA-DRB5 and TNFSF10 have been proved to be key players in the pathogeneses of many autoimmune or rheumatic diseases." (PMID 35309355, 2022).
scoliosis (1 paper, 2012). A congenital or acquired spinal deformity characterized by lateral curvature of the spine. "In patients with elbow contractures and scoliosis (sideways curving of the spine), an up-regulation of three inflammatory genes was found when compared with patients without those features, namely HLA-DRB1 and HLA-DRB5, (FC = 8.8, 7.1), and GZMK (FC = 1.3; FDR = 0%)." (PMID 22479353, 2012).
Sepsis (1 paper, 2025). Sepsis is defined as life-threatening organ dysfunction caused by a dysregulated host response to infection. "In sepsis, Microglia 1 exhibited strong upregulation of pro-inflammatory genes (e.g., GPNMB, CXCR4, HLA-DRB5) and downregulation of BBB-supportive genes (e.g., SPARCL1, MAP1B), indicating a highly reactive phenotype." (PMID 41030458, 2025).
staphylococcus aureus infection (1 paper, 2018). An infectious process in which the bacteria Staphylococcus aureus is present. "Among which, we also performed the PPI network of several DEGS including C3, HLA-DRB5, ICAM1 and HLA-DRB1, ITGAM, and CFD that involved in the staphylococcus aureus infection signaling pathway." (PMID 30186855, 2018). "Target DEGs of differentially expressed miRNAs were significantly enriched in staphylococcus aureus infection involving four DEGs (HLA-DRB1, HLA-DRB5, C3, and ICAM), which suggested that inflammation may be a factor for STC." (PMID 30186855, 2018). "HLA-DRB1, HLA-DRB5, C3, and ICAM were significantly involved in staphylococcus aureus infection." (PMID 30186855, 2018).
thymic adenocarcinoma (1 paper, 2017). "Recently, a case of thymic adenocarcinoma showed the deletion of the HLA-DRB5 locus on array comparative genomic hybridization (CGH) analysis." (PMID 28506304, 2017). "Until now, other putative driver mutations except the deletion of the HLA-DRB5 locus have not been discovered yet in thymic adenocarcinoma." (PMID 28506304, 2017).
type 2 diabetes (1 paper, 2022). "In a meta-analysis that included three cohorts, the absence of HLA-DRB5 was associated with an increased risk of type 2 diabetes (P = 0.001)." (PMID 35321340, 2022).
viral infections (1 paper, 2024). "In addition, HLA-DRB5/DRB1 has been proposed to affect viral infection susceptibility." (PMID 37962454, 2024). "Genes that may impact viral infections are ABCA7 and HLA-DRB5/DRB1." (PMID 37962454, 2024).
vitiligo (1 paper, 2023). Generalized well circumscribed patches of leukoderma that are generally distributed over symmetric body locations and is due to autoimmune destruction of melanocytes. "We verified that FOS and HLA-DRB5 expression was upregulated in PBMC from vitiligo patients compared with HCs by analyzing Bluk-RNA seq data from GEO database." (PMID 38077333, 2023).